SIRT1 (sirtuin 1)
Diseases named in the same sentence as SIRT1 in open-access papers (continued):
Sharing a sentence is not in itself a finding about the gene and the disease.
esophageal cancer (9 papers, 2019 to 2025). A primary or metastatic malignant neoplasm involving the esophagus. "The drug-resistant oesophageal cancer cells exhibit increased autophagy and SIRT1 expression, both of which are linked to enhanced cell migration and the EMT." (PMID 39403142, 2024). "SIRT1 consistently promotes the progression of esophageal cancer (EC)." (PMID 40567502, 2025). "Since HOXC‐AS1 functioned in SIRT1 mRNA stability, we investigated whether HOXC‐AS1 was involved in the development of esophageal carcinoma via SIRT1." (PMID 36510377, 2023). "SIRT1, a NAD+-dependent deacetylase involved in the regulation of DNA repair and metabolism, was considered as an independent survival risk factor in esophageal cancer and its overexpression was associated with worse OS (HR = 1.776, P = 0.009) and disease-free survival (DFS) (HR = 1.642, P = 0.017)." (PMID 34252349, 2021). "In addition, SIRT1 was related to malignant transformation in drug-resistant esophageal cancer cells." (PMID 34252349, 2021). "Previous studies revealed that aberrant expression of SIRT1 has been noted in many solid tumours including esophageal carcinoma, and the overexpression of SIRT1 is responsible for radiation resistance and poor prognosis in patients with esophageal cancer treated with chemotherapy and radiotherapy." (PMID 31684999, 2019). "A better understanding of the biological correlation between ADC and protein SIRT1 holds the promise of discovering predictive and prognostic biomarkers that might be helpful in the management of esophageal carcinoma." (PMID 31684999, 2019). "Additionally, a SIRT1 inhibitor effectively suppressed tumor growth in a mouse xenograft model without significant toxicity, suggesting that SIRT1 plays a key role in autophagy-driven drug resistance in oesophageal cancer." (PMID 39403142, 2024). "In esophagus cancer, MNX1-AS1 was also demonstrated to facilitate the proliferative and invasive capacities of tumor cells through regulating the miR-34a/SIRT1 signaling axis." (PMID 33685348, 2021).
glaucoma (9 papers, 2014 to 2024). Increased pressure in the eyeball due to obstruction of the outflow of aqueous humor. "Previous studies have demonstrated the dysfunction of SIRT1 in ocular diseases, and the knockdown of SIRT1 was associated with cataract, glaucoma, AMD, and DR." (PMID 33379248, 2020). "Here we found that the levels of Sirt-1 in glaucoma lymphocytes were significantly higher than in controls, a finding associated with increased content of F2-isoprostanes as marker of oxidative stress." (PMID 24936186, 2014). "Consistent with the changes found in lymphocytes, analysis of plasma confirmed increased protein levels of sirtuin-1, higher in patients with glaucoma as to compare with the healthy control group." (PMID 24936186, 2014). "In addition, sirtuin 1 (SIRT-1), which encodes an NAD+-dependent deacetylase, has been shown to protect RGCs in an optic nerve crush and an IOP model of glaucoma." (PMID 39201561, 2024). "Higher expression of SIRT1 protects against diseases related to oxidative stress-induced ocular damage, such as cataracts, age-related macular degeneration, and optic nerve degeneration in glaucoma patients." (PMID 29249955, 2017). "Interestingly, we found significantly (P < 0.05) higher levels of sirtuin-1 in lymphocytes of patients with glaucoma than in the control group." (PMID 24936186, 2014). "Interestingly, a decreased expression of SIRT1 has been observed in the TM of glaucoma patients." (PMID 34156425, 2021). "Our work presents the first composite analysis of Sirtuins in the retinal neurons of mice, rats, and humans, and suggests that increasing the expression and activity of SIRT1 may be beneficial for the treatment of glaucoma and other age-related eye dysfunction." (PMID 29249955, 2017). "Moreover, our study provides evidence for SIRT1 activators in the treatment of glaucoma." (PMID 29249955, 2017).
head and neck cancer (9 papers, 2021 to 2025). A primary or metastatic malignant neoplasm affecting the head and neck. "In head and neck cancer, the activation of SIRT1 facilitates the epithelial-mesenchymal transition (EMT), thereby enhancing cancer cells’ susceptibility to ferroptosis." (PMID 40109363, 2025). "In head and neck cancer, manipulation of several EMT markers/drivers, including E‐cad, ZEB1, SIRT1, and the miR‐200 family, causes dramatic changes in ferroptosis sensitivity." (PMID 37496319, 2023). "Six unique analyses showed significant differences for SIRT1 in head and neck cancer, of which two were upregulated and four were downregulated." (PMID 35136826, 2022). "A study in head and neck cancer cells showed that silencing SIRT1 expression can inhibit epithelial-mesenchymal transition and decrease ferroptosis, while SIRT1 agonists can promote ferroptosis." (PMID 36093072, 2022). "Many studies have revealed a protumorigenic effect of Sirt1 in many types of cancer, but its role in head and neck cancer remains controversial." (PMID 33727672, 2021). "In this study, we found that ROS-induced cell death of head and neck cancer cells is initially regulated by Sirt6 and Sirt1." (PMID 33727672, 2021). "A potential correlation between SIRT1 expression and prognosis for head-neck cancer may warrant further discussion." (PMID 38567911, 2024). "In other words, SIRT1 overexpression could result in ferroptosis in head and neck cancer and human papillary carcinoma cells, thus preventing tumor progression, which might be attributed to the mechanism that SIRT1 overexpression affected cellular homeostasis." (PMID 37153222, 2023). "In paclitaxel-tolerant persister head and neck cancer (HNC) cell lines, SIRT1 activation promotes ferroptosis by increasing mitochondrial fatty acid oxidation via facilitating the dispersion and localization of lipid droplets on mitochondria." (PMID 40109363, 2025). "The expression of SIRT1 did not appear to significantly contribute to predicting overall survival at any stage of head-neck cancer." (PMID 38567911, 2024).
hearing loss (9 papers, 2018 to 2025). "MiR-34a and lncRNA H19 were also involved in the SIRT1-mediated regulation of cytoprotective functions, indicating a possible synergistic role of specific ncRNAs in the development of hearing loss." (PMID 38298898, 2023). "In our previous study, we found that ginsenoside Rd ameliorated auditory cortex injury associated with military aviation noise-induced hearing loss (NIHL) by activating the SIRT1/PGC-1α signaling pathway." (PMID 35620603, 2022). "Additionally, Sirt1-deficient mice develop hearing loss, and heterozygous Sirt1 transgenic B6 mice exhibit reduced oxidative damage and slower ARHL progression." (PMID 39959464, 2025). "This suggested that consumption of NAD+ by SIRT1 may be crucial in protection against cisplatin-induced hearing loss." (PMID 39204103, 2024). "Recent studies have reported that SIRT1 dysfunction is related to abnormal oxidative stress in cochlear cells and hearing loss, and resveratrol treatment exhibits a protective effect against oxidative stress in cochlear hair cells by enhancing SIRT1 deacetylase activity." (PMID 35620603, 2022). "SIRT1 plays a crucial role in hearing loss, especially ARHL." (PMID 36204138, 2022). "To demonstrate whether the activation of SIRT1 attenuates CDDP-mediated hearing loss in mice, we examined the effect of SRT1720 on CDDP-induced hearing loss." (PMID 30692914, 2018). "However, whether SIRT1 dysregulation was a causal factor in hearing loss was unclear." (PMID 39204103, 2024). "SIRT1 (n = 29) and SIRT3 (n = 19) have been the most studied sirtuins, while SIRT2 (n = 1) and SIRT7 (n = 1) were rarely studied in connection to hearing loss." (PMID 39204103, 2024). "In summary, our results revealed that HFD consumption-mediated downregulated expression of SIRT1 and SIRT3 and aging together lead to hearing loss." (PMID 33889076, 2021). "Additionally, MNAM-mediated cochlear upregulation of SIRT1 and SIRT3 protein expression levels exerted a preventive effect against the HFD- and aging-induced hearing loss." (PMID 33889076, 2021). "However, a previous report has suggested that the half expression of SIRT1 did not lead to ARHL, whereas the lack of SIRT1 expression led to hearing loss." (PMID 33889076, 2021).
multiple myeloma (9 papers, 2016 to 2025). "An increased expression of SIRT1 was observed in myeloma cells lines and may be associated with treatment resistance." (PMID 39727710, 2024). "In an investigation of the effects of PI3K suppression on multiple myeloma cells, the inhibitory effect of pan-PI3K inhibition on the survival of both KMM-1 and RPMI 8226 cells via the induction of SIRT1-mediated G2/M arrest was also highlighted." (PMID 32160736, 2020). "The aim of this study was to investigate the effects of a 6-week cycle of Nordic walking training intervention on the serum levels of vitamin D metabolites (25-OH-D3 and 1,25-OH-D3) and vitamin D receptors VDR, SIRT1, SIRT 3, and FOXO3a in patients with multiple myeloma." (PMID 39727710, 2024). "Although not specific for SIRT1, HDAC inhibitors were found to down-regulate GLUT1 expression and to inhibit hexokinase 1 enzymatic activity in multiple myeloma cells, underscoring that acetylation plays a key role in regulation of glycolytic metabolism." (PMID 27494892, 2016).
prostate tumor (9 papers, 2013 to 2025). "In this study, we investigated the effect of MSCs overexpressing an NAD-dependent deacetylase sirtuin 1 (MSCs-Sirt1) on prostate tumor growth, and we analyzed the underlying mechanisms." (PMID 27764779, 2016). "This elevated expression of SIRT1 in malignant cells was further confirmed through immunohistochemical analyses of human prostate tumors." (PMID 39796040, 2024). "Together, these results indicate that CXCL10 recruits NK cells, thus contributing to the MSCs-Sirt1-induced prostate tumor suppression in mice." (PMID 27764779, 2016). "Our results show that MSCs accelerate prostate tumor growth, whereas MSCs-Sirt1 significantly suppresses tumor growth." (PMID 27764779, 2016). "SirT1 has also been shown to inhibit androgen receptor-dependent cell proliferation in prostate tumor cells." (PMID 24223900, 2013). "Our results showed that prostate tumor xenografted overexpressed SIRT1." (PMID 37894275, 2023). "Melatonin can inhibit SIRT1 to modulate MMP2 activity, which was shown to impact the degradation of the ECM and exert anti-proliferative effects on prostate tumor cells." (PMID 39796199, 2025). "One interesting study revealed that Astragalus polysaccharides (APS) significantly reduces SIRT1 expression, impairing lipid metabolism by modulating the AMPK/SREBP1 axis, thereby curbing prostate tumor growth and invasion." (PMID 39796040, 2024). "The resulting pro-inflammatory milieu significantly suppresses prostate tumor growth, an effect diminished when IFN-γ and CXCL10 pathways are inhibited, highlighting SIRT1’s role in immune-mediated tumor suppression." (PMID 39796040, 2024). "Interestingly, SIRT1 expression was known to be significantly increased in many tumors, such as colon tumors, leukemia, non-melanoma skin cancer, and prostate tumors." (PMID 37894275, 2023).
renal failure (9 papers, 2010 to 2025). "SIRT1 makes a contribution towards innate cell apoptosis reduction in the kidney, kidney failure retardation caused by increase in age, inflammation reduction, renal interstitial fibrosis inhibition, blood pressure regulation, autophagy induction and protection in DKD." (PMID 30110438, 2018). "In summary, our results demonstrate that FGF21 ameliorates cisplatin-induced nephrotoxicity through SIRT1, preventing kidney failure and tubular cell damage." (PMID 32210821, 2020). "SIRT1-modified hUCMSCs might work as a promising therapeutic strategy for the treatment of peritoneal dialysis-induced peritoneal damage and fibrosis." (PMID 32811535, 2020).
status epilepticus (9 papers, 2015 to 2024). Status epilepticus is defined as a continuous seizure lasting more than 30 min, or two or more seizures without full recovery of consciousness between any of them. "In the present study, we noted that the Sirt1 mRNA underwent a significant increase after KA-induced status epilepticus, followed by an increase in the SIRT1 protein level." (PMID 31340436, 2019). "Our aim was to investigate the potential role of mitochondrial biogenesis in the SIRT1/PGC-1α pathway using our previously reported kainic acid (KA)-induced status epilepticus model." (PMID 31340436, 2019). "Particularly, we noted that SIRT1 expression was enhanced in the rat hippocampus following status epilepticus and upregulated PGC-1α expression." (PMID 31340436, 2019). "The reason lies in the fact that reduced oxidative stress in HUVECs was also abolished by an autophagy inhibitor 3-MA, and one report that SIRT1-induced autophagy mediated suppressed oxidative stress by SAL in status epilepticus." (PMID 31146723, 2019). "A recent report showed that SIRT1 expression and activity were enhanced in the rat hippocampus following status epilepticus, and augmented the PGC-1α/mitochondrial antioxidant signaling pathway." (PMID 31340436, 2019). "Limited studies have explored the mechanism of the SIRT1 pathway in chronic epilepsy or status epilepticus." (PMID 31340436, 2019). "In the situation of status epilepticus, we propose that the nuclear full-length SIRT1, apart from deacetylating PGC-1α, is a protective mechanism of SIRT1 via mitochondrial biogenesis." (PMID 31340436, 2019). "Western blot analysis of the total protein prepared from the right hippocampal CA3 subfield revealed a significant increase in the expression of SIRT1 from 1 to 48 h with a peak level at 3 h after KA-induced experimental status epilepticus." (PMID 31340436, 2019). "A recent study showed that SIRT1 expression and activity were enhanced in the rat hippocampus following status epilepticus and augmented the PGC-1α/mitochondrial antioxidant signaling pathway." (PMID 31340436, 2019). "Interestingly, it was previously shown that the down-regulation of SIRT1 in the rat hippocampus following status epilepticus led to decreased mitochondrial respiratory chain activity, impaired mitochondrial biogenesis, and higher oxidative stress." (PMID 38892612, 2024). "SIRT1 prevents oxidative stress and mitochondrial dysfunction in many neuronal disease models, such as autistic spectrum disorder, intracerebral hemorrhage, ischemia/reperfusion, status epilepticus, and PD, through the PGC-1α pathway." (PMID 36379180, 2022). "As mitochondrial biogenesis is another important feature of the SIRT1/PGC-1α signaling pathway, in the present report, we demonstrated that SIRT1 regulates the mitochondrial biogenesis machinery and affects the hippocampal neuronal cell fate following KA-induced status epilepticus." (PMID 31340436, 2019). "However, many PGC-1α-positive neurons were detected in the hippocampal CA3b area 6 h after experimental status epilepticus in animals with pre-treatment of Sirt1 sense or Sirt1 scrambled ODN." (PMID 31340436, 2019). "We first examined whether SIRT1 expression in the hippocampal CA3 subfield was induced following experimental status epilepticus." (PMID 31340436, 2019). "A previous study showed that SIRT1 activation could enhance the PGC-1α/mitochondrial antioxidant system pathway in pilocarpine-induced status epilepticus." (PMID 31340436, 2019). "Here, we explored the transcriptional response of genes associated with polycomb repressive complex (PRC) 1 (Ring1A, Ring1B, and Bmi1) and PRC2 (Ezh1, Ezh2, and Suz12), as well as additional transcriptional regulators Sirt1, Yy1, and Yy2, in a mouse model of status epilepticus (SE)." (PMID 25806020, 2015).
status epilepticus (continued). "The results suggest that the SIRT1 signaling pathway may play a pivotal role in mitochondrial biogenesis, and could be considered an endogenous neuroprotective mechanism counteracting seizure-induced neuronal cell damage following status epilepticus." (PMID 31340436, 2019). "A temporal correlation was presented between the increased SIRT1 and upregulated PGC-1α in the hippocampal CA3 subfield after KA-induced status epilepticus." (PMID 31340436, 2019). "Oxidative stress is known to be involved in status epilepticus; in a kainic-acid-induced model of status epilepticus, salidroside showed a neuroprotective effect by regulating AMPK/SIRT1/FOXO1 signaling." (PMID 30705774, 2019). "Increased SIRT1, PGC-1α, and mitochondrial biogenesis machinery were found in the hippocampus following experimental status epilepticus." (PMID 31340436, 2019). "SIRT1 expression and activity have been found to be restored in the hippocampal CA3 region of rats after kainic acid-induced status epilepticus, and increase the peroxisomal proliferator-activated receptor α (PGC-1α)/mitochondrial antioxidant coactivator signaling pathways." (PMID 35744955, 2022). "Corresponding to the change in SIRT1 expression after the pre-treatment of antisense ODN against Sirt1, both the Pgc-1α mRNA level and PGC-1α protein expression reduced in 6 h after experimental status epilepticus." (PMID 31340436, 2019).
systemic sclerosis (9 papers, 2016 to 2025). A chronic disorder, possibly autoimmune, marked by excessive production of collagen which results in hardening and thickening of body tissues. "In systemic sclerosis, a decrease in circulating SIRT1 and SIRT3 levels enhances the severity of cutaneous fibrosis and interstitial lung disease." (PMID 37483618, 2023). "Resveratrol ameliorates BLM-induced skin inflammation and fibrosis in systemic sclerosis mice by activating SIRT1/mTOR signalling." (PMID 37483618, 2023). "In the last few decades, a growing number of studies have explored the contribution of SIRTs to the pathogenesis of systemic sclerosis, highlighting the significant anti-fibrotic effects of SIRT1 and SIRT3." (PMID 37483618, 2023). "The activation of sirtuin 1 by resveratrol has been demonstrated to ameliorate tissue fibrosis in dystrophic cardiomyopathy or systemic sclerosis." (PMID 26934322, 2016). "Interestingly, knockdown of SIRT1 can effectively inhibit TGF-β1 signaling and exerts potent antifibrotic effects, establishing SIRT1 as a key regulator of fibroblast activation in systemic sclerosis." (PMID 26753996, 2016). "Both SIRT1 and SIRT3 serum levels were significantly reduced in patients with systemic sclerosis compared to those in controls." (PMID 37483618, 2023). "However, recent studies have indicated that SIRT1 is a crucial regulator of fibroblast activation in systemic sclerosis (SSc), and TGF-β signaling and collagen expression can be effectively inhibited by the knockdown of SIRT1." (PMID 30455644, 2018). "SIRT1 expression was reduced in patients with systemic sclerosis and TGF-β-dependent experimental fibrosis patients, but this reduction was not sufficient to counteract the excessive activation of TGF-β signalling in systemic sclerosis." (PMID 37483618, 2023).